ANXA5 (annexin A5)
Description:
This protein is an anticoagulant protein that acts as an indirect inhibitor of the thromboplastin-specific complex, which is involved in the blood coagulation cascade.
Synonyms: CPB-I; PP4; PAP-I; ANX5; ENX2; VAC-alph; RPRGL3; HEL-S-7
Tractability: Small molecule: it has a binding pocket of medium quality. Antibody: its Gene Ontology location is reachable by antibodies, with high confidence. PROTAC: UniProt records ubiquitination sites on it; ubiquitination databases record sites on it; its protein half-life has been measured.
Target class: Ion channel; Annexin; Other ion channel
Gene: Protein-coding gene on chromosome 4 (121,667,396 to 121,697,061, reverse strand). Ensembl gene ENSG00000164111.
Subcellular location (Human Protein Atlas): Nuclear membrane
Pathways (Reactome):
Hemostasis: Platelet degranulation
Gene Ontology:
Molecular function: calcium-dependent phospholipid binding; protein binding; phosphatidylserine binding; phospholipase inhibitor activity; phospholipid binding; calcium ion binding
Biological process: negative regulation of apoptotic process; signal transduction; negative regulation of coagulation
Cellular component: extracellular exosome; extracellular matrix; focal adhesion; membrane; cytoplasm; cytosol; extracellular region; sarcolemma; vesicle membrane; endothelial microparticle; external side of plasma membrane
Genetic constraint (gnomAD): Loss-of-function variants: 24 observed, 23.03 expected, observed/expected ratio (o/e) 1.04, 90% interval 0.75 to 1.47. The upper end of that interval is the gene's LOEUF score, 1.47, which puts it in group 6 of 6, group 1 being the genes least tolerant of losing a copy. Missense variants: 199 observed, 239.03 expected, observed/expected ratio (o/e) 0.83, 90% interval 0.74 to 0.94. Synonymous variants: 80 observed, 84.57 expected, observed/expected ratio (o/e) 0.95, 90% interval 0.79 to 1.14.
Homologues: Orthologues: chimpanzee ANXA5 (100% identical), macaque ANXA5 (99% identical), dog ANXA5 (98% identical), pig ANXA5 (98% identical), rabbit ANXA5 (93% identical), guinea pig ANXA5 (93% identical), mouse Anxa5 (93% identical), rat Anxa5 (92% identical), tropical clawed frog anxa5 (74% identical), zebrafish anxa5b (63% identical), zebrafish anxa5a (58% identical), Drosophila melanogaster AnxB9 (48% identical), and 1 more. Paralogues in human: ANXA4 (57% identical), ANXA6 (57% identical), ANXA8L1 (56% identical), ANXA8 (56% identical), ANXA11 (52% identical), ANXA3 (49% identical), ANXA7 (48% identical), ANXA2 (44% identical), ANXA1 (43% identical), ANXA13 (43% identical), ANXA10 (38% identical), ANXA9 (37% identical).
Diseases named in the same sentence as ANXA5 in open-access papers:
ANXA5 is named in the same sentence as 367 diseases in open-access papers, as found by Europe PMC text mining. Sharing a sentence is not in itself a finding about the gene and the disease. The quoted sentences say what the papers report.
breast cancer (278 papers, 2003 to 2026). A primary or metastatic malignant neoplasm involving the breast. "Our data indicated that the expression of CORO1A and ANXA5 are significantly associated with multiple clinic-pathological features of breast cancer, such as age, menopause status, disease stage, nodal metastasis status, and molecular subtypes." (PMID 33407865, 2021). "Thus, the expression of CORO1A and ANXA5 may serve as the potential diagnostic indicators in breast cancer, and DPP4 might play a significant role in the tumorigenesis and progression of prostate cancer." (PMID 33407865, 2021). "The expression levels of MYD88, DAXX and ANXA5 were significantly upregulated in the control samples compared to breast cancer samples." (PMID 41357233, 2025). "It has been reported that annexin A5 plays a role in promoting tumorigenesis and metastasis in various cancers such as pancreatic adenocarcinoma, sarcoma, breast cancer, and prostate cancer." (PMID 37759912, 2023). "McKernan also incorporated annexin A5 (ANXA5)-functionalized single-walled carbon nanotubes (SWCNTs) and photothermal therapy into the treatment of primary breast cancer in mice receiving anti-CTLA-4 antibody therapy." (PMID 37860188, 2023). "ANXA5 was also found to be differentially expressed in a variety of other cancers, such as breast cancer, hepatocellular carcinoma, and lung squamous cell carcinoma." (PMID 35884419, 2022). "Several studies have shown that the upregulation of annexin A5 is observed in different types of cancers, such as colorectal adenocarcinoma, breast cancer, and cervical cancer, and is capable of promoting tumorigenesis and progression in these cancers." (PMID 35805203, 2022). "The expression of ANXA5 was significantly lower in breast cancer patients than normal controls in subgroup analysis based on gender, age, menopause status, disease stage, nodal metastasis status, and molecular subtypes (all P < 0.001)." (PMID 33407865, 2021). "Eventually, CORO1A and ANXA5 as the representative target genes for breast cancer and DPP4 for prostate cancer were made the following analysis." (PMID 33407865, 2021). "Van Rite et al35 have reported that a fusion protein consisting of AnxA5 and an antitumour protein domains is able to recognize and bind to exposed PS by breast cancer cells and enhance the antitumour effect in vitro." (PMID 31468674, 2019). "AnxA4 and AnxA5 are expressed in breast cancer tissues and upregulation of AnxA4 promotes chemo-resistance of breast cancer." (PMID 29416802, 2018). "Throughout the years of investigation Annexin A1 (AnxA1), Annexin A2 (AnxA2), Annexin A3 (AnxA3), Annexin A4 (AnxA4), Annexin A5 (AnxA5), Annexin A6 (AnxA6), and Annexin A8 (AnxA8) have all been identified as potential modulators of breast cancer progression." (PMID 29416802, 2018). "In breast cancer, ANXA5 aids in membrane repair, essential for metastatic survival." (PMID 39400959, 2024). "Previous studies have shown that ANXA5 can influence tumor progression through m6A or PCD, but its role in breast cancer remains to be further investigated." (PMID 41357233, 2025). "Then, we developed a risk prognostic model based on expression levels of PIK3CA, SESN3, ANXA5, MYD88, DPP4, DAXX, and CRIP1 to predict clinical outcomes in patients with breast cancer." (PMID 41357233, 2025). "We showed recently that ANXA5 and ANXA6 silencing prevents metastasis of breast cancer cells in vivo." (PMID 38092984, 2023). "In breast cancer, studies have proven that ANXA2, ANXA4, ANXA5, ANXA6, and ANXA7 are required for repair in breast cancer cells, indicating that a network of annexins participate in the plasma membrane repair response." (PMID 34484309, 2021).
breast cancer (continued). "For other targets including annexin A5 (ANXA5), prothrombin (F2) and renin (REN), there was no firm evidence to link their functions directly to breast cancer progression, and they were less significant in the PPI network, which meant that they might be not important targets for LF triterpenoids." (PMID 33246450, 2020).
melanoma (198 papers, 2007 to 2025). A malignant, usually aggressive tumor composed of atypical, neoplastic melanocytes. "SNPs in the Anxa5 gene are associated with the risk of pregnancy-related venous thrombosis, preeclampsia and malignant melanoma." (PMID 33810523, 2021). "A Western blot confirmed a significant decrease of Annexin A5 protein amount in melanoma cell lines." (PMID 24743186, 2014). "Indeed, treatment of melanoma xenografts with AnxA5 reduced tumour growth, increased necrosis in tumour tissues and most strikingly, inhibited angiogenesis by downregulating VEGF production." (PMID 33810523, 2021). "Additionally, the results obtained from previous 2D-PAGE assays made in our laboratory suggested a decrease of both proteins ILKAP and Annexin A5 in melanoma cell lines compared to primary melanocytes." (PMID 24743186, 2014). "Therefore, the reduction of Annexin A5 protein amount observed in melanoma cell lines may be changing motile capacity of the tumor cells." (PMID 24743186, 2014). "The results showed a weak reduction in the ANXA5 gene expression and a significant decreased gene expression of ILKAP (p-value <0.05 after applying Student’s t-test) in the melanoma cell lines studied in comparison with primary melanocytes." (PMID 24743186, 2014). "In order to confirm an alteration in the expression levels of ANXA5 and ILKAP in MM, quantitative measurement of these genes’ expression was investigated in 10 melanoma cell lines and 3 primary melanocytes using quantitative real time PCR." (PMID 24743186, 2014). "Furthermore, the biological relevance of these genes in MM is supported by in vitro experiments, which show a decrease in the transcription levels of ANXA5 and ILKAP in melanoma cells compared to normal melanocytes." (PMID 24743186, 2014).
lung carcinoma (132 papers, 2003 to 2025). "We identified aptamer-associated protein biomarkers for lung cancer such as vimentin, annexin A2, annexin A5, histone 2B, neutrophil defensin, and clusterin." (PMID 26061649, 2015). "However, the associations of ANXA5 with lung cancer progression, invasion and metastasis are very complex and remains poorly understood." (PMID 27684953, 2016). "Anxa5 plays a key role in lung cancer pathogenesis by regulating crucial signaling pathways associated with NSCLC." (PMID 34912233, 2021). "The data indicate that annexin A5 confers gefitinib resistance in lung cancer by inhibiting apoptosis and G2/M cell cycle arrest, and is thus a potential therapeutic target in non-small cell lung cancers resistant to EGFR tyrosine kinase inhibitors." (PMID 29784046, 2018). "This study was designed to determine the mechanism of ANXA5 in lung cancer with a hope to obtain useful information to provide a new therapeutic target." (PMID 27684953, 2016). "In summary, our quantitative proteomics approach identified ANXA5 as a pleotropic regulator in the lung cancer cells." (PMID 27684953, 2016). "As a result, 70 differentially expressed proteins (from a total of 314) were identified, which may be useful in creating a molecular signature of ANXA5 in lung cancer." (PMID 27684953, 2016). "However, the precise biological role of ANXA5 in the living lung cancer cell is still far from clear." (PMID 27684953, 2016). "And the ANXA5 transfected H520 cells might be served as an important and ideal cellular model to investigate the mechanism of ANXA5 in lung cancer." (PMID 27684953, 2016). "Taken together, ANXA5 appears to have pleotropic effects, as it modulates multiple key signaling pathways, supporting the potential usefulness of ANXA5 as a potential target in lung cancer." (PMID 27684953, 2016). "Additionally, they are in accordance with recent studies demonstrating that radiolabeled Annexin A5 allows for the in vivo monitoring of cell death in experimental lung cancer treated by cytotoxic therapy as well as in animal models of myocardial infarction." (PMID 26393949, 2015). "Interestingly, 99mTc-BTAP-Annexin A5 uptake 24–48 h after the first course of chemotherapy was significantly related to survival and progression-free survival in lung cancer and lymphoma patients." (PMID 24216991, 2013). "This study might provide a new insight into the mechanism of ANXA5 in lung cancer." (PMID 27684953, 2016). "To investigate the function of ANXA5, we generated gefitinib-resistant PC9R and H4006R lung cancer cells by exposure to escalating doses of gefitinib." (PMID 29784046, 2018). "Thus, ANXA5 is an important mediator of resistance to EGFR tyrosine kinase inhibitors, and is a potential therapeutic target in recalcitrant lung cancers." (PMID 29784046, 2018). "Additionally, ANXA5 is significantly expressed in non-papillary bladder cancer, and lung cancer patients with high Cir–ANXA seven expression tend to have a poorer prognosis." (PMID 36936694, 2023).
glioma (120 papers, 2006 to 2025). A benign or malignant brain and spinal cord tumor that arises from glial cells (astrocytes, oligodendrocytes, ependymal cells). "A study reported that the ANXA5 polymorphism increased the risk of glioma in patients and suggested a poor prognosis." (PMID 37759912, 2023). "ANXA5 expression was shown to be considerably higher in individuals with gastric cancer, and ANXA5 polymorphism pairs were found to alter glioma susceptibility and prognosis." (PMID 37124542, 2023). "The differentially expressed and mutational profile of glioma was constructed, and four targetable antigens (ANXA5, FKBP10, MSN, and PYGL) were further confirmed." (PMID 34512630, 2021). "Four glioma antigens, namely ANXA5, FKBP10, MSN, and PYGL, associated with superior prognoses and infiltration of APCs were selected." (PMID 34512630, 2021). "Further study on the effects of ANXA5 may contribute to understanding the potential mechanism associated with MAPK/CD44 pathway in glioma progression." (PMID 40607003, 2025). "ANXA5 is associated with the angiogenesis and progression of glioma." (PMID 38639785, 2024). "Thus, we believe that ANXA5 is an important pathogenic factor in glioma." (PMID 40607003, 2025). "ANXA5 expression was significantly upregulated in glioma cell lines, especially in U251 and SHG44 cells, we then selected them for further functional experimental studies." (PMID 40607003, 2025). "The knockdown of ANXA5 dramatically inhibited cell proliferation, migration, and invasion as well as promoted cell apoptosis of glioma cells." (PMID 40607003, 2025). "More importantly, ANXA5 was positively correlated with Cluster of differentiation-44 (CD44) according to the Chinese Glioma Genome Atlas (CGGA) database." (PMID 40607003, 2025). "Meanwhile, we found that the expression of CD44 was monitored by ANXA5, and ANXA5 promoted the migration and proliferation of glioma cells via the MAPK/CD44 pathway." (PMID 40607003, 2025). "For the expression levels and the diagnostic value of ANXA5, we further investigated the effects of ANXA5 in glioma progression." (PMID 40607003, 2025). "And, H&E staining showed that ANXA5 knockdown crushed the compact structure of tumor tissues from intracranial and subdermal glioma models, respectively." (PMID 40607003, 2025). "In this study, we aimed to identify the hub genes and investigate the pathophysiological significance of ANXA5 in glioma." (PMID 40607003, 2025). "Furthermore, ANXA5 knockdown significantly inhibited the migration and proliferation of glioma cells in vitro and in vivo." (PMID 40607003, 2025). "Taken together, these results suggested that ANXA5 is highly expressed in glioma cells and it may contribute to the malignant characteristics of U251 and SHG44 cells." (PMID 40607003, 2025). "As a result, we confirmed the up-regulation of ANXA5 in glioma cell lines, and further elucidated its biological roles and underlying molecular mechanisms in vivo and in vitro, which may provide novel targets for personalized diagnosis and treatment of glioma." (PMID 40607003, 2025). "Taken together, our data showed that ANXA5 could contribute to cell proliferation and metastasis of glioma by targeting the MAPK/CD44 axis." (PMID 40607003, 2025). "The expression levels of ANXA5 in glioma cell lines were detected by qRT-PCR and Western blotting." (PMID 40607003, 2025). "For ANXA5, STAT1, CD44, CAV1, and ANXA2, LGG patients with high expression possessed a worse overall survival, while low expression of MAPT was associated with poor overall survival among patients with primary gliomas." (PMID 40607003, 2025). "However, the expression, biological roles, and potential molecular mechanisms of ANXA5 in gliomas are still unclear." (PMID 40607003, 2025). "Hence, the roles of ANXA5 on the proliferation, migration, invasion, cell cycle, and apoptosis of glioma cells as well as its relevant mechanism were investigated." (PMID 40607003, 2025).
glioma (continued). "Importantly, CCK-8, colony formation, and flow cytometric assays consistently showed that ANXA5 knock-down inhibited glioma cell proliferation and altered the cell cycle distribution." (PMID 40607003, 2025). "Abnormally expressed ANXA5 is related to angiogenesis and the progression of glioma." (PMID 34512630, 2021). "Therefore, we might consider that ANXA5 supports multifarious malignant phenotypes of glioma cells through the MAPK/CD44 signaling pathway." (PMID 40607003, 2025). "Additionally, ANXA5 knockdown significantly inhibited the tumor growth in vivo, suggesting that it could be a promising therapeutic target in gliomas." (PMID 40607003, 2025). "Overall, ANXA5 could potentially be used as a novel biomarker for high-grade gliomas." (PMID 38639785, 2024). "Likewise, AnxA5 upregulation promoted tumourgenicity of glioma cells in nude mice." (PMID 33810523, 2021). "Four glioma antigens were identified, including FKBP prolyl isomerase 10 (FKBP10), glycogen phosphorylase L (PYGL), annexin A5 (ANXA5), and moesin (MSN), which were correlated with elevated APC infiltration and better prognoses." (PMID 40948290, 2025). "To further investigate the roles of ANXA5 in U251 and SHG44 cells, we established an intracranial glioma model using NC-sh and shANXA5#1 transfected U251-luc cells as well as a xenograft model using transfected SHG44 cells." (PMID 40607003, 2025). "The amplified expressions of ANXA5, FKBP10, MSN, and PYGL were correlated with favorable prognosis OS and DFS of glioma, which exert pivotal roles in glioma development and progression." (PMID 34512630, 2021). "Hence, the mechanism of how ANXA5, STAT1, CD44, CAV1, MAPT, and ANXA2 contributed to the gliomas still need further research." (PMID 40607003, 2025). "Finally, six genes (ANXA5, STAT1, CD44, CAV1, MAPT, and ANXA2) with the highest degree values were selected as the hub genes for glioma by using the cytoHubba plugin for expression level and prognosis analyses." (PMID 40607003, 2025). "In summary, a systematic bioinformatics analysis of DEGs demonstrated that ANXA5, STAT1, CD44, CAV1, MAPT, and ANXA2 might serve as potential biomarkers and therapeutic targets for glioma." (PMID 40607003, 2025). "The results showed that the expression levels of ANXA5 were higher in glioma cell lines compared with the human normal glial cell line HEB." (PMID 40607003, 2025). "The correlation analysis between ANXA5 and CD44 indicated that CD44 might play an essential role in malignant behaviors involved in ANXA5 in glioma." (PMID 40607003, 2025). "The protein-protein interaction (PPI) network analysis showed that ANXA5, STAT1, CD44, CAV1, ANXA2, and MAPT may serve as candidate biomarkers in glioma diagnosis." (PMID 40607003, 2025). "Altogether, these findings suggested that ANXA5, STAT1, CD44, CAV1, MAPT, and ANXA2 might play a vital role in the pathogenesis of gliomas." (PMID 40607003, 2025). "According to research, non-angiogenic gliomas are characterized by express higher levels of ANXA5 (with a 2.1-fold increase) and angiogenic glioma (with a 3.4-fold increase) as compared to normal tissues." (PMID 37660060, 2023). "Four antigens ANXA5, FKBP10, MSN, and PYGL were promising to develop mRNA vaccine against glioma." (PMID 34512630, 2021). "Generally, these results suggested that ANXA5, STAT1, CD44, CAV1, MAPT, and ANXA2 might play a critical role in the pathogenesis of glioma, suggesting that the hub genes might be a promising biomarker of glioma." (PMID 40607003, 2025). "On the other hand, AnxA5 knockdown impeded tumourigenesis in subcutaneous xenografts from renal cell carcinoma, with the latter two studies suggesting an involvement of PI3K/Akt signaling and implicating AnxA5 as a potential biomarker in glioma and renal cell carcinoma." (PMID 33810523, 2021).